NPM1 (nucleophosmin 1)
Diseases named in the same sentence as NPM1 in open-access papers (continued):
Sharing a sentence is not in itself a finding about the gene and the disease.
leukemia (continued). "In HOVON-SAKK trials, a positive MRD result after induction chemotherapy is defined as ≥0.1% of CD45-expressing cells with a leukemia associated immunophenotype (LAIP) for MFC-MRD or, for AML with mutated NPM1, >10−4 NPM1 copies using reverse transcriptase polymerase chain reaction." (PMID 36300090, 2022). "In mouse models of NPM1-mutated/FLT3-ITD AML, venetoclax plus menin inhibitor was superior to the menin inhibitor alone, in eliminating leukemic cells (including leukemia stem/progenitor cells), decreasing Bcl-2 and Bcl-xL levels, and significantly prolonging mice OS." (PMID 36008542, 2022). "However, the blasts in AML with monocytic differentiation (e.g., acute monocytic/monoblastic leukemia, AML with mutated NPM1), acute erythroid leukemia, and acute megakaryocytic leukemia are typically negative for CD34." (PMID 36245043, 2022). "The anti-leukemia ability of ATO and ATRA support the further application in NPM1-mutated AML." (PMID 36237321, 2022). "NPM1 plays an important role in both solid tumors and leukemia." (PMID 34899858, 2021). "Moreover, our data are in agreement with a recent paper that showed an interaction of NPM1 with myeloid differentiation protein-2 (MD-2), a protein that associates with TLR4, in human leukemia monocytic cell line THP-1." (PMID 34134693, 2021). "The FLT3-mutation like pattern was enriched in NPM1 and DNMT3A mutant leukemias." (PMID 33592069, 2021). "Our observation that NPM1 VAF decreased below 2.5% in all cases with morphologic leukemia-free state, also proved that NPM1 mutations do not occur in the preleukemic state." (PMID 34153064, 2021). "Interestingly, this effect was least pronounced in the NPM1 mutant cell line (OCI-AML3), consistent with previous studies suggesting that nuclear export of FOXM1 by mutant NPM1 contributes to the relative chemosensitivity of this leukemia." (PMID 34711181, 2021). "Furthermore, the persistence of leukemia-associated mutations, such as FLT3-ITD, NPM1, and CEBPA mutations, after the initial course of standard induction chemotherapy imparts a significantly increased risk of subsequent leukemic relapse and death." (PMID 34422653, 2021). "Here, the cellular localization of HOTAIRM1 in leukemia cell lines remained the same regardless of the mutational status of NPM1." (PMID 34615546, 2021). "Of the genes more highly expressed in female FLT3‐ITD‐positive AML, the hedgehog signalling mediator GLI2 has been associated with FLT3‐ITD‐mutated leukaemia, while HOXB‐AS3 is reportedly upregulated in NPM1‐mutated AML, and has been implied to contribute in regulation of AML cell‐cycle progression." (PMID 34101344, 2021). "To date, two menin-MLL1 inhibitors (K0539, NCT04067336 and SNDX-5613, NCT04065399) have demonstrated preclinical activity in HOXA/MEIS1 genes-driven leukemias, including MLL-r and NPM1-mutant AML, and have entered clinical testing with a focus on patients with MLL-rearrangements or NPM1 mutations." (PMID 34698191, 2021). "Thus, NPM1 mutation is an AML-driving lesion and maintains leukemia mainly through a gain-of-function by the NPM1c+." (PMID 33782403, 2021). "Mouse models of mutated NPM1 (NPM1c) support the importance of NPM1c as a cooperative event in leukemogenesis, but not to initiate leukemia." (PMID 32188030, 2020). "Given the promising results in murine leukemia models with co-occurring mutations, we then evaluated the ex vivo activity of TP-0903 and TKIs in human primary samples with coexisting recurrent mutations (e.g., FLT3-ITD, IDH1/2, ASXL1, DNMT3A, NPM1, and SRSF2)." (PMID 33268594, 2020). "In patients with no mutations of both FLT3-ITD and NPM1, additional mutations in other leukemia-related genes proved to influence disease evolution." (PMID 32796597, 2020). "Mutations in the nucleophosmin gene (NPM1) also belong to important prognostic factors in AML and might be associated with anti-leukemia immune response." (PMID 31185600, 2019).
leukemia (continued). "Considering the fact that INPP4B has protein tyrosine phosphatase activity and Ser/Thr phosphatase activity, whether NPM1 might be a substrate of the INPP4B protein in leukemia remains to be clarified." (PMID 29343273, 2018). "Our results indicate that INPP4B promotes leukemia cell survival via SGK3 activation, and INPP4B might be a potential target in the treatment of NPM1-mutated AML." (PMID 29343273, 2018). "Increased NPM1 expression was also detected in human-derived leukemia cell lines." (PMID 30126426, 2018). "Surprisingly, our data demonstrate that loss or gain of INPP4B did not appear to affect AKT activation in NPM1-mutated leukemia cells." (PMID 29343273, 2018). "All NPM1 transcripts were increased in leukemia compared to HV." (PMID 30126426, 2018). "In the case of upregulation, we were going to distinguish particular transcripts to test whether NPM1 transcripts are similarly increased in both leukemia types and which transcripts contribute the most to the change of expression." (PMID 30126426, 2018). "However, to date, NPM1 expression in leukemia patients has rarely been reported and previous studies were conducted on a protein level or gene level without distinguishing transcript variants." (PMID 30126426, 2018). "Taken together, these findings indicate that INPP4B expression might be upregulated by NPM1-mA via ERK/Ets-1 signaling in leukemia cells." (PMID 29343273, 2018). "Importantly, NPM1 mutations are always retained at relapse and this led to the generally accepted concept that NPM1 should be specifically targeted in this kind of leukemia." (PMID 28920929, 2017). "We then tested the effects of NPM1-mA depletion on myeloid differentiation in leukemia cells." (PMID 27669739, 2016). "NPM1 mutations result in the aberrant expression of the NPM1 protein in the cytoplasm rather than the nucleus, stimulating myeloid proliferation and leukemia development." (PMID 26959069, 2016). "Importantly, several proteins implicated in leukemia pathobiology emerged amongst the novel PPP3CA interactors such as Rb, NPM1, BCL11b, GSK3β and KDM1 (also known as LSD1)." (PMID 27304189, 2016). "Because of the recently discovered miRNA signature of NPM1-mutated AML, we hypothesized that miRNA might be involved in the NPM1-mA mediated inhibition of differentiation in leukemia cells." (PMID 27669739, 2016). "In line with our finding of autophagy in AML cells, a recent report detailing the human autophagy interaction network across cancer types demonstrated increased autophagy-associate mRNA levels in several subtypes of AML including NPM1-mutated, MLL-fusion and CBFB-MYH11-fusion leukemias." (PMID 27732946, 2016). "Therefore, our results highlight miR-10b and KLF4 as potential therapeutic targets and novel prognostic markers for NPM1-mA positive leukemia." (PMID 27669739, 2016). "NPM1 gene at chromosome 5q35 is involved in recurrent translocations in leukemia and lymphoma." (PMID 20877721, 2010). "Notably, such DNMT3A-mutated pre-leukemic cells were found in patients whose bulk leukemia cells also carried NPM1 and FLT3-ITD mutations, implying DNMT3A lesions arose earlier and persisted after the transient remission of the NPM1/FLT3-ITD-mutant leukemic clone." (PMID 40651916, 2025). "Importantly, menin’s interaction with both wild-type MLL and MLL fusion proteins is necessary to maintain oncogenic activation of Hox genes, as well as the Hox cofactors MEIS1 and PBX3, and downstream targets such as FLT3 in both MLLr and NPM1 mutant leukemias." (PMID 39336822, 2024). "In addition to its established oncogenic roles in MLLr and NPM1 mutant leukemias, menin may also play a role in NUP98 fusion and UBTF tandem duplication (UBTF-TD) acute leukemias." (PMID 39336822, 2024).
leukemia (continued). "We demonstrated that cytotoxic T cells specific for the mutated antigen can be reproducibly expanded, and these cells efficiently recognize and lyse leukemia blasts or other cell types carrying the NPM1-mutated antigen, without causing damage to normal hematopoietic cells." (PMID 37345068, 2023). "Downregulation of circ-NPM1 or up-regulation of its binding miR-345-5p suppressed cell cycle progression, colony formation, and the capacity of migration and invasion and increased apoptosis rate and sensitivity of leukemia cells to leukemia cells Adriamycin (ADM)." (PMID 37124518, 2023). "The other patient whose leukemia blasts did not respond to AQ had an NPM1 mutation." (PMID 36831684, 2023). "The physical interaction of NUP98 fusion proteins with MLL complexes at promoters in combination with the similar leukemia-associated gene signature in NUP98-r, NPM1-mut, and MLL-r AML raises the question whether NUP98-r AML is dependent on the Menin–MLL interaction." (PMID 37520776, 2023). "However, the mechanism of high autophagic levels in NPM1-mutated leukemia has not yet been fully clarified." (PMID 36675134, 2023). "Many studies have reported that mutations and rearrangements in NPM1 are found in 35% of patients with AML, and NPM1 mutational persistence significantly affects the relapse rate and might be more resistant to chemotherapy in leukaemia." (PMID 37251542, 2023). "Similarly, the combination of menin inhibitors with FLT3 inhibitors resulted in an enhanced inhibitory effect on the proliferation and stimulatory induction of apoptosis of primary FLT3-mut leukemic blasts and of leukemia cells in a murine model of leukemia promoted by NPM1-mut and FLT3-ITD." (PMID 37509445, 2023). "An expansion of testing into other types of leukaemia led to a trial enrolling 591 AML patients in 1999 with Falini and colleagues demonstrating a high proportion of cases showed cytoplasmic localisation of NPM1 in AML, the primary cause of which was identified as mutations in exon 12 of NPM1." (PMID 34576201, 2021). "Moreover, by stimulation with dendritic cells pulsed with different NPM1-mutated peptide mixtures in a 13-day culture, we were able to expand ex vivo leukemia-specific CD8+ and CD4+ CTLs from four NPM1-mutated AML patients, as well as to prime leukemia-specific responses in three healthy donors." (PMID 34502069, 2021). "Therefore mutations in NPM1 and Mir142 may provide a convergent role in IDH-mutant leukemias, namely to activate HOX gene expression." (PMID 33173219, 2020). "Furthermore, none of the normal human sequences present in databanks match those of the 11 C-terminal residues of the NPM1 mutants, suggesting that this aminoacidic sequence may serve as a leukemia-specific antigen." (PMID 30783516, 2019). "Some therapeutically-targetable leukemia antigens originate from oncogenesis itself and are leukemia cell-specific, such as the BCR/ABL1 fusion protein in CML and Philadelphia (Ph)+ ALL, PML/RAR-α in acute promyelocytic leukemia, FLT3-ITD and mutated NPM1 in AML and IDH1/2." (PMID 29466292, 2018). "NPM1 may be a preferable target, because of its presence on leukemia stem cells." (PMID 28638379, 2017). "Besides leukemia, involvement of NPM1 has also been reported in several solid cancers." (PMID 27553022, 2016). "However, animal studies revealed that these imbalances alone may not always lead to full-fledged disease, indicating the requirement for NPM1 mutations and cooperating mutations in other genes, like DNA methyltransferase 3A (DNMT3A), to allow the progression to overt leukemia." (PMID 38255885, 2024). "Consistent with our data, the GMP gene signature was significantly positively enriched in NPM1-deficient human leukemic cells compared to control shREN cells, and the GMP-like gene signature was significantly negatively enriched, suggesting that NPM1 might be a driver of leukemia." (PMID 37130348, 2023).
leukemia (continued). "It is worth mentioning that a Dot1L and menin combinatory inhibitors approach has been already proposed for therapy of some hematological malignancies including NPM1-mutant and MLL-rearranged leukemias." (PMID 35850772, 2022). "Mutant NPM1 maintains the leukemic state through the expression of HOX, while mixed-lineage leukemia-specific chromosomal aberrations or abnormalities interfere with normal hematopoiesis by regulating the overexpression of HOX genes." (PMID 36002858, 2022). "Recently, evidences of complementary activities of menin and DOT1L inhibitors in NPM1-mutant and MLL-rearranged leukaemia have been demonstrated." (PMID 36333801, 2022). "Two different cooperation models of mutant NPM1 with two different signal transduction genes, FLT3-ITD and NRASG12D, showed rapid leukemia onset in mice." (PMID 34944812, 2021). "Brunetti and colleagues targeted XPO1 with selinexor in an NPM1c model, which led to the relocalization of NPM1 to the nucleus, inhibition of the HOX genes and an anti-leukemia effect." (PMID 32545659, 2020). "The TPM of the NPM1 gene was equal to 1492 in AML-T0 (median), 752 in AML-T1 and 799 in HV (mean), indicating a twofold increase in leukemia at the time of diagnosis and a decrease after therapy to the level typical for HV." (PMID 30126426, 2018). "AML biomarkers NPM1, FLT3, CXCR4, MMP9 and IGF-IR are also present in AML cell derived exosomes, along with mRNAs involved in leukemia development." (PMID 27191983, 2016). "However, the specific role of miR-10b in NPM1-mutated leukemia has not been fully elucidated." (PMID 27669739, 2016). "More recently, mutations in DNMT3A, but not NPM1, were identified in pre-leukaemic HSCs from patients with double DNMT3A/NPM1 mutant AML, further supporting the leukaemia-initiating pedigree of mutant DNMT3A." (PMID 25056697, 2014). "Taken together, these data suggest that csNPM1 is presented on many in vitro leukemia models and in vivo primary murine AML models, regardless of NPM1 mutation status." (PMID 40269321, 2025). "Moreover, driver genes, as RAS, FLT3, NPM1, EVI1 and KMT2A shape the interaction between polyamine metabolic pathway and leukemia-supporting functions, resulting in selective vulnerabilities, as unveiled by drugs targeting PRMT5." (PMID 40603833, 2025). "In the absence of DNMT3A mutations, NPM1 mutations lead to the downregulation of the CIITA gene, thereby inhibiting the expression of CLIP protein and HLA molecules, which helps leukemia cells evade recognition by CD8+ T cells." (PMID 40861464, 2025). "In MLLr and NPM1 mutant leukemias, however, Hox gene expression is aberrantly activated either by the MLL fusion proteins or by aberrant wild-type MLL activity mediated by NPM1 mutants, inhibiting differentiation and resulting in increased cell proliferation and survival that drives leukemogenesis." (PMID 39336822, 2024). "Second, relevant genetic subgroups were excluded (i.e. mutant-NPM1 and FLT3 ITD leukemias), which may specifically benefit from such an approach as suggested by our multivariate analysis." (PMID 38195541, 2024). "In contrast, favorable risk is defined by mutated NPM1 without concomitant FLT3-ITD mutation, bZIP in-frame mutated CEBPA as well as core-binding factor leukemias." (PMID 38571944, 2024). "5/7 patients in the low group had negative MRD after cycle 2, the remaining two had no detectable leukemia-associated immunophenotype at diagnosis and negative MRD but positive NPM1 MRD, respectively." (PMID 36611026, 2023). "In this work, we also observed that cytoplasmic TP53INP2 was more abundant in leukemia cells with NPM1-mA than those without NPM1-mA." (PMID 36675134, 2023).
leukemia (continued). "3.1.d—Mutation in NPM1, FLT3 and DNMT3A AML with three-way interaction among NPM1, DNMT3A and FLT3 occurs in around 6% of AML and is characterized by high leukemia stem cell (LSC) frequency, aberrant immunophenotype (with low CD34 and high CD56) and overexpression of hepatic leukemia factor (HLF)." (PMID 36831522, 2023). "Leukemia-associated antigens (e.g., CD33 and CD123) are usually strongly expressed in AML cells (especially in NPM1-mutated AML cells) but can also be detected in normal hematopoietic stem cells and in extramedullary tissues (e.g., CD123 in endothelial cells)." (PMID 36008542, 2022). "Overall, these results indicate that, despite the binding between the two occurring in T-ALL cells, B23/NPM1 inhibition does not appear to have a critical role in the anti-leukemia effects of CIGB-300." (PMID 32471246, 2020). "Given the importance of B23/NPM1 inhibition for the effect of CIGB-300 in solid tumors, we next investigated whether a similar mechanism could account for CIGB-300 anti-leukemia effects by silencing NPM1 in HPB-ALL cells." (PMID 32471246, 2020). "In The Cancer Genome Atlas (TCGA) project for AML, several genes such as FLT3, NPM1, DNMT3A, CEBPA, IDH1 and IDH2, were found to be recurrently mutated, as well as others never documented before in the pathogenesis of leukemia, including EZH2." (PMID 32188030, 2020). "This hypothesis was further confirmed, as we found that INPP4B mRNA levels were increased upon ectopic overexpression of NPM1-mA in THP-1 and K562 leukemia cell lines." (PMID 29343273, 2018). "Chimeric proteins between NPM1 and the retinoic acid receptor-α gene (RARα) or between NPM1 and the myelodysplasia/myeloid leukemia factor 1 (MLF1) have also been reported in rare cases of leukemia." (PMID 27553022, 2016). "Although NPM1-mutated AML patients without FLT3-ITD has a good prognosis, those who underwent allogeneic HSCT showed a particularly long-term disease control, probably due to specific graft-versus leukemia effect." (PMID 36008542, 2022). "Indeed, NPM1-mutated C-terminal aminoacidic sequences are not found in either malignancies different from AML or normal tissues, resulting in leukemia-specific neoantigens considered optimal target for immunotherapy." (PMID 34502069, 2021). "In leukemia, the NPM1 expression has not been widely studied so far." (PMID 30126426, 2018). "The majority of these earlier studies showed that NPM1 mutation without FLT3ITD is associated with better clinical outcomes, and allo-HST conferred no benefit in this patient group similar to the core binding-factor leukemia patient group." (PMID 28197208, 2017). "NPM1 is usually a secondary or downstream mutation, whereas mutations in DNMT3A, ASXL1, IDH1/2, and TET2 occur very early during clonal evolution but are typically not sufficient to cause leukemia on their own." (PMID 28197208, 2017). "In both these AML cases the ALDHbright compartment contains neither an FLT3-ITD nor an NPM1 mutation (AML-808 and 3G, AML-575 upper panels), indicating HSC, while the ALDHlow compartment has both these leukemia-associated mutations (AML-808 and 3G, AML-575 middle panels), indicating LSC." (PMID 24244383, 2013). "In multivariate analysis considering known prognostic factors (age, gender, type of leukemia, cytogenetic risk group, WBC, FLT3/ITD, and NPM1 mutant status), EKLF expression (yes/no) remained an independent favorable prognostic factor for EFS (HR 0.4504, 95%CI 0.2115-0.9589, P = 0.038)." (PMID 22676581, 2012). "The incidence and significance of NPM1 deletion in human leukemia have not been elucidated." (PMID 20877721, 2010). "Of clinical relevance, therapeutic targeting of either NPM1 or FLT3-ITD mutations might thus have a transient benefit in restraining disease progression and debulking the leukemia but is unlikely to be curative since will not target the AML-initiating/preleukemic cells." (PMID 31936647, 2020).
leukemia (continued). "While the expression of the stem‐related gene HOXA10 is not significantly different between NPM1, KMT2Ar, and NUP‐r harboring leukemias, we found that HOPX expression is significantly different between KMT2Ar and NUP‐r in comparison to NPM1." (PMID 41178390, 2025).